NUCKS1 (nuclear casein kinase and cyclin dependent kinase substrate 1)
Diseases named in the same sentence as NUCKS1 in open-access papers (continued):
Sharing a sentence is not in itself a finding about the gene and the disease.
tumor (14 papers, 2009 to 2025). "Previous studies demonstrated that NUCKS1 associates with cell proliferation in tumor, while the silencing of NUCKS1 facilitates corneal wound healing following alkali injury." (PMID 34696757, 2021). "NUCKS1 positive expression was found to be significantly associated with certain clinicopathological characteristics, including the tumor grade, lymph node involvement and the presence of distant metastases." (PMID 25187794, 2014). "Moreover, NUCKS1 is highly expressed in a variety of malignancies and acts as a tumor-associated protein regulating cellular transcription and repair." (PMID 37582772, 2023). "Moreover, NUCKS1 is a chromatin-associated protein with a role in the DNA damage response and in HR, a DNA repair pathway critical for tumor suppression." (PMID 29619377, 2018). "In in vivo studies, a high level of NUCKS1 may be associated with tumor progression and recurrence in cervical squamous cell carcinomas (CSCCs)." (PMID 29619377, 2018). "In addition, associations between NUCKS1 and other tumor subtype markers, including estrogen receptor (ER), progesterone receptor (PR), human epidermal growth factor receptor 2 (HER2), Ki-67 and cytokeratin 5/6 (CK 5/6), were investigated." (PMID 25187794, 2014). "Furthermore, a significant association between NUCKS1 and tumor grade was found." (PMID 25187794, 2014). "In breast cancer, for example, NUCKS1 acts as a powerful promoter of tumor growth and invasiveness, facilitating cellular proliferation and invasion." (PMID 39736854, 2025). "In gastric cancer, NUCKS1 significantly contributes to tumor progression through mTOR-Beclin1 pathway, leading to poor patients’ outcome." (PMID 39736854, 2025). "Among which, PI3K/Akt possessed as the most significantly enriched pathway in both HCT-8 and LoVo cells, which is regulated by NUCKS1 and involved in tumor progression." (PMID 39736854, 2025). "Our findings indicated that the depletion of ASNS impaired the effects of NUCKS1 on tumor weight and volume." (PMID 37528150, 2023). "The tumor promotion mechanism of NUCKS1 was investigated by RNA sequencing analysis, and NUCKS1 transcriptionally upregulated ASNS expression by binding its promoter." (PMID 37528150, 2023). "An increasing number of studies have revealed that NUCKS1 is increased in multiple cancers and involved in tumor development." (PMID 37528150, 2023). "Compared with control cells, 143B cells with NUCKS1 knockdown significantly suppressed tumor formation, as indicated by reduced tumor weights and sizes." (PMID 37528150, 2023). "NUCKS1 plays an important role in non-neoplastic diseases such as Parkinson disease and bipolar disorder." (PMID 37582772, 2023). "The subsequent immunohistochemistry analyses assay was performed to detect the resected 143B xenograft tumor tissues from the control and NUCKS1 knockdown groups using the Ki-67 and Cleaved Caspase 3 antibodies." (PMID 37528150, 2023). "The results showed that the average expression levels of NUCKS1 were significantly higher in tumor tissues than those in the normal tissues." (PMID 26989074, 2016). "Using gene-specific knockdown of NUCKS1 in human cells, we have shown that NUCKS1 is a chromatin-associated protein with a novel role in the DDR and in HR, a DNA repair pathway critical for tumor suppression." (PMID 27542204, 2016).
tumor (continued). "Western blot analysis was used to confirm NUCKS1 expression in FFPE tumor samples and adjacent normal samples." (PMID 25187794, 2014). "The intricate mechanisms through which NUCKS1 exerts its influence involve extensive gene expression alterations and the activation of downstream signaling cascades, collectively fostering conditions favorable for uncontrolled tumor growth and metastasis." (PMID 39736854, 2025). "Furthermore, NUCKS1 depletion inhibits—while its overexpression promotes—xenograft tumour growth, suggesting a direct role in tumourigenesis." (PMID 34845229, 2021). "Remarkably, NUCKS1 is critical for tumor suppression and the DNA damage response." (PMID 29619377, 2018). "In addition, the results confirmed that NUCKS1 immunoreactivity was associated with positive Ki-67 reactivity, with 89.7% of the tumor samples with positive NUCKS1 expression showing a high Ki-67 index (14%)." (PMID 25187794, 2014). "In addition, siRNA silencing of NUCKS1 significantly suppresses tumor growth." (PMID 29619377, 2018). "In human cells, however, NUCKS1 deficiency after siRNA-mediated knockdown impairs DNA damage signaling, DSB repair and genome stability, suggesting that this protein may function as a tumor suppressor." (PMID 27542204, 2016). "PRDX6, MAGOHB, NUCKS1, DCAF13, and TXN displayed opposite trends on their potential facilitation of CTL function as well as correlations with immune checkpoints and TILs (tumor-infiltrating lymphocytes) compared to ITGAL, ITGAX, and TMEM119 in NSCLC." (PMID 37835514, 2023). "For instance, the human homologous genes for the murine genes upregulated by taxifolin in LL2 tumors, including Prdx6, Magohb, Nucks1, Dcaf13, and Txn1, acted to facilitate the CTL-mediated killing of tumor cells, as shown by their negative T cell dysfunction values." (PMID 37835514, 2023).
infection (1 paper, 2021). The state of being infected such as from the introduction of a foreign agent such as serum, vaccine, antigenic substance or organism. "siRNA knockdown efficiency at the time of infection was confirmed by qRT-PCR, with a low of 77% efficiency for NUCKS1, and averaging over 95% efficiency for most targets." (PMID 34548480, 2021).
NUCKS1 also shares sentences with these, for which no sentence is quoted: Alzheimer disease (2 papers); depression (2); endometrial cancer (2); Parkinson's (2); adenosis (1); atypical ductal hyperplasia (1); brain cancer (1); breast disease (1); ductal carcinomas in situ (1); essential tremor (1); female reproductive cancers (1); Fibroadenoma (1); gastric tumor (1); Huntington disease (1); invasive carcinoma (1); latent infection (1); leukemia (1); lobular carcinomas (1); pancreatic cancer (1); schizophrenia (1); Sepsis (1); skin cutaneous melanoma (1); skin tumors (1); squamous cell carcinoma (1); T-cell leukemia (1); uveal melanoma (1).